PRL (prolactin)
Diseases named in the same sentence as PRL in open-access papers (continued):
Sharing a sentence is not in itself a finding about the gene and the disease.
schizophrenia (continued). "Thus, future studies should examine the impact of serum prolactin on managing patients with schizophrenia." (PMID 28320371, 2017). "Negligible effects were seen with respect to changes in fasting glucose, total cholesterol, low-density lipoprotein cholesterol, prolactin elevation, and triglycerides' levels, at least in contrast with alternative SGAs and/or higher average dose regimens used for schizophrenia patients." (PMID 28573138, 2017). "Thus, our data indicate that the Df(h15q13)/+ mouse has decreased speed of processing and reduced recruitment of putative fast-spiking interneurons in the PrL and this phenotype corresponds with observations in schizophrenia patients." (PMID 26983414, 2016). "In addition, we sought to identify potential moderators of reduced BMD at skeletal sites in schizophrenia, including gender, age, smoking, prolactin (PRL) levels and body mass index (BMI)." (PMID 27696144, 2016). "In addition to the effectiveness of aripiprazole monotherapy for schizophrenia, its mechanism of action (partial agonist/modulator at D2 receptors) makes it useful in normalizing serum prolactin levels when combined with other antipsychotics." (PMID 26427051, 2015). "Research in this area may lead to an improved understanding of schizophrenia, as well as a better delineation of the effects of prolactin on social behaviour and cognition in humans." (PMID 24800074, 2014). "In contrast, the exaggerated prolactin response to serotonin in resistant schizophrenia is indicative of serotonergic hyperfunction; this is consistent with the fact that clozapine, an antagonist at multiple serotonin receptors, is the treatment of choice in this population." (PMID 24800074, 2014). "Besides this, a variety of studies over the past four decades have examined other facets of the relationship between prolactin and schizophrenia and call for a reappraisal of this relationship." (PMID 24800074, 2014). "Fourth, a moderate increase in prolactin, brought about by antipsychotics, may play a role in alleviating the positive symptoms of schizophrenia." (PMID 24800074, 2014). "The finding that patients with schizophrenia have an exaggerated prolactin response to stress may be relevant here." (PMID 24800074, 2014). "Further research into the genetic links between prolactin and schizophrenia, the exact relationship between prolactin and central dopamine, the significance of circadian changes in prolactin, and the effects of prolactin on human social behaviour will provide a true test of this proposal." (PMID 24800074, 2014). "Like other hormones, prolactin shows circadian variations in its rhythm and may be used to track circadian rhythm changes in schizophrenia." (PMID 24800074, 2014). "The next question to be considered is whether elevated prolactin is related to specific symptoms or dimensions of schizophrenia, which is a multidimensional entity." (PMID 24800074, 2014). "Our finding of higher prolactin/growth hormone and insulin/growth hormone ratios in female first onset schizophrenia patients suggests that this effect could also be sex-specific." (PMID 24244349, 2013). "Present study aims to evaluate the efficacy and tolerability of aripiprazole (10-15mg/day) in the treatment of Indian patients of schizophrenia and to see its effect on QTc interval, prolactin levels, serum lipids, plasma sugar and weight gain in these patients." (PMID 21206777, 2004). "Additionally, the 8-week follow-up in this study might not be sufficient to reflect the long-term outcome of patients with schizophrenia in real-world settings, and the long-term effects of aripiprazole on PRL require further investigation." (PMID 39267697, 2024). "However, in real-life diagnostic settings, it remains uncertain whether aripiprazole consistently lowers prolactin levels in patients with various levels of baseline prolactin at the acute phase of schizophrenia." (PMID 39267697, 2024).
schizophrenia (continued). "According to several studies, pituitary alterations are likely involved in schizophrenia and psychosis onset, and patients with schizophrenia possibly have an exaggerated prolactin response to stress, as a consequence of the genetic variations in prolactin or autoimmune mechanisms." (PMID 39061992, 2024). "In the secondary findings, we found that older age was a protective factor for HPRL, and one study also found that antipsychotic-derived high levels of PRL decline with age in patients with schizophrenia, which may be attributed to the fact that the gonads shrink with age." (PMID 36816406, 2023). "Thus, in these patients with schizophrenia or other mood disorders, surgical resection of the prolactinoma can be considered, but monitoring of prolactin levels and closer surveillance of the prolactinoma may be the best option." (PMID 38143631, 2023). "Therefore, prolactin-sparing antipsychotics are recommended for female patients with schizophrenia." (PMID 36979271, 2023). "The prolactin (PRL) pathway may contribute to the comorbidity of schizophrenia and T2DM." (PMID 33315097, 2021). "Therefore, homocysteine and/or prolactin levels may serve as candidate prognostic markers for schizophrenia." (PMID 33995058, 2021). "PRL levels in schizophrenia patients may be related to BMD and bone metabolism." (PMID 32788631, 2020). "Hence, monitoring of prolactin levels after switching to aripiprazole may help avoid such rebound in schizophrenia." (PMID 33228575, 2020). "Therefore, routine monitoring of PRL after switching to aripiprazole may be useful in adjusting the treatment strategy to avoid a rebound in psychotic symptoms in chronic schizophrenia patients." (PMID 33228575, 2020). "More recent studies have shown these same neuroendocrine and metabolic abnormalities in antipsychotic naïve patients with first episode psychosis (FEP), rising the hypothesis that schizophrenia itself may be related to an abnormal regulation of prolactin secretion and to impaired glucose tolerance." (PMID 30068291, 2018). "Although previous research has shown that antipsychotics can cause a rise in prolactin levels, there is a lack of evidence regarding head-to-head comparisons of adverse event profiles of several antipsychotics in the treatment of schizophrenia in pediatric populations." (PMID 29805808, 2018). "However, an analysis from a separate 6-day phase I study in stable subjects with schizophrenia found similar prolactin pharmacokinetic profiles (Cmax and AUC) when subjects received the highest recommended dose of paliperidone ER (12 mg/day) compared with an average dose of risperidone (4 mg/day)." (PMID 21299844, 2011). "However, given the long-term effects of HPRL and the fact that schizophrenia patients usually need to maintain the treatment plan during hospitalization after discharge, it is necessary to monitor PRL levels during hospitalization and choose treatment plans with less impact on PRL." (PMID 40964426, 2025). "Taken together, we speculate that PRL and bone metabolism markers may be related to the underlying mechanisms of reduced BMD in male chronic schizophrenia patients, thus providing a useful viewpoint to monitor the bone health of male schizophrenia patients on long term antipsychotics treatment." (PMID 32788631, 2020). "In this regard, the relationship between PRL and BMD in schizophrenia patient needs further investigation." (PMID 32788631, 2020). "For male schizophrenia patients, generalized linear regression analyses used BMD as dependent variable, and TRACP-5b, PRL and BAP as covariates." (PMID 32788631, 2020). "Patients with schizophrenia had significantly higher levels of BMI, T3, ALK-P, prolactin, and FSH than the controls." (PMID 32764574, 2020).
schizophrenia (continued). "We also examined the possible relation between the relative pituitary volume and serum prolactin levels in a subsample of 72 (27 ARMS and 45 schizophrenia) subjects, which showed a significant positive correlation (rho = 0.293, p = 0.012)." (PMID 30473669, 2018). "Also, altered levels of hormones (prolactin, cortisol, progesterone, and growth hormone) in blood have been observed in people with schizophrenia, indicating that functions of multiple components of the hypothalamic-pituitary-adrenal-gonadal axis may be affected." (PMID 26909022, 2016). "Meaney and O’Keane followed premenopausal female patients with schizophrenia over the course of one year and compared lumbar and femoral BMD changes between those taking prolactin-sparing AP and those taking prolactin-raising AP." (PMID 26309037, 2015). "Ziprasidone, a benziso-thiazolyl-piperazine derivative, is an atypical antipsychotic effective across positive, negative, and affective symptoms of schizophrenia, with fewer extrapyramidal, cognitive, prolactin-related, or anticholinergic side effects." (PMID 41226471, 2025). "Ziprasidone targets a broad spectrum of schizophrenia symptoms, including positive, negative, and affective symptoms, with minimal motor, cognitive, prolactin-related, or anticholinergic side effects." (PMID 41226471, 2025). "The D2 antagonism is associated with its efficacy in the treatment of schizophrenia, while the potent 5-HT2A antagonism improves the negative symptoms of schizophrenia and reduces extrapyramidal side effects and prolactin levels." (PMID 38539614, 2024). "Consistent with our hypotheses, patients with schizophrenia randomized to MPGT achieved greater improvements in symptoms and reported lower plasma prolactin levels." (PMID 37801319, 2023). "Estrogens, testosterone, and PRL, but also pregnenolone, allopregnenolone, DHEA, and DHEA-S may play an important role in the pathogenesis of schizophrenia." (PMID 37047464, 2023). "Early studies in many cases revealed reduced or normal PRL levels in patients not yet treated for schizophrenia." (PMID 37047464, 2023). "Data on PRL levels in patients with schizophrenia, but not yet treated with antipsychotics, are inconclusive." (PMID 37047464, 2023). "Prolactin levels can be elevated even in antipsychotic-free schizophrenia patients without apparent physical illness, so patients with high levels were not excluded from this study." (PMID 37564244, 2023). "A small meta-analysis published in 2016 also confirmed that patients with schizophrenia and related conditions had higher PRL levels than controls (people without psychiatric disorders)." (PMID 37047464, 2023). "However, correlation analysis showed significant correlations between TRACP-5b (r = − 0.300, P < 0.01), BAP (r = 0.301, P < 0.01), PRL (r = − 0.431, P < 0.01) and BMD in men with schizophrenia." (PMID 32788631, 2020). "The correlation between the pituitary volume and working memory in schizophrenia was not significant when we used prolactin level as a controlling factor (rho = −0.23, p = 0.122)." (PMID 30473669, 2018). "To date, no systematic reviews have comparatively examined the prolactin-related adverse event profiles of both the FGAs and SGAs in schizophrenia and schizophrenia spectrum disorder pediatric patients." (PMID 25312992, 2014). "While evidence-based approaches examining efficacy and safety outcomes have been reported, no review has evaluated prolactin-based adverse events for antipsychotic treatments in schizophrenia and schizophrenia spectrum disorders." (PMID 25312992, 2014). "Other studies report changes in prolactin levels but not specifically in schizophrenia or schizophrenia spectrum disorders." (PMID 25312992, 2014). "Based on various short term and long term studies, aripiprazole has been found to be effective in schizophrenia and has no significant adverse effect on QTc prolongation, prolactin, serum lipids, and has a low potential for weight gain." (PMID 21206777, 2004).
schizophrenia (continued). "Secondly, although PRL testing is part of the clinical pathway for treating schizophrenia in China, there were still a few patients who did not have their PRL levels tested during hospitalization, which may result in incomplete or biased data." (PMID 40964426, 2025). "In summary, the present study demonstrated that patients experiencing acute episode of schizophrenia in a real-world clinical environment may have elevated PRL levels, regardless of their previous antipsychotic medication." (PMID 39267697, 2024). "It is not easy to down-regulate increased PRL levels in patients with schizophrenia." (PMID 36833950, 2023). "DRD2 methylation is closely related to children’s psychological trauma and alcohol dependence and is a marker of schizophrenia showed that increased DRD2 promoter methylation is correlated with decreased DRD2 mRNA levels and increased PRL mRNA levels in the pituitary." (PMID 35865960, 2022). "However, our results demonstrated that no dose-dependent effect of olanzapine on prolactin levels in patients with schizophrenia exists." (PMID 34421613, 2021). "However, emerging evidence has suggested additional connections between prolactin and psychiatric disorders, where negative correlations have been found between systemic prolactin levels and measures of positive symptoms in schizophrenia patients." (PMID 34767585, 2021). "This longitudinal study suggests that long-term clozapine treatment may protect BMD compared to prolactin-raising and non-clozapine prolactin-sparing antipsychotics among patients with schizophrenia." (PMID 30846868, 2019). "The advantages of this medication have been repeatedly stressed: it is relatively safe in terms of motor, metabolic and endocrine side effects (it does not usually alter prolactin levels), and it proved to be comparable to other SGAs in terms of efficacy for the treatment of schizophrenia." (PMID 30071042, 2018). "The relationship of the serum levels of testosterone, prolactin, dehydroepiandrosterone (DHEA) and/or its sulfate conjugate (DHEA-S), ACTH, cortisol, progesterone, gonadotropins, and estradiol with schizophrenia have been evaluated by some studies and diverse findings have been obtained." (PMID 27293968, 2016). "Similarly, it has been demonstrated that the mean plasma prolactin level was increased in early-onset schizophrenia spectrum psychosis patients compared with no-early-onset patients." (PMID 27829454, 2016). "In a large nationwide survey in almost 900 people with schizophrenia taking antipsychotic medications, almost 60% reported nonadherence, with prolactin and endocrine related effects being one of the commonly cited reasons, decreasing the odds of adherence by about 30%." (PMID 23968123, 2013). "However, APDs use may not be the only contributing factor, as increased PRL levels have been observed in many treatment-naïve first-episode schizophrenia patients." (PMID 40964426, 2025). "Among the investigated gene loci, the genes involved in the dopamine–prolactin pathway, including the neuropeptide Y gene (NYP) and prolactin gene (PRL), may also attract attention to their contribution to the comorbidity of schizophrenia and metabolic syndrome." (PMID 35806096, 2022). "In this study we moved from the hypothesis that at least a subgroup of patients with schizophrenia spectrum psychosis may have a specific vulnerability for abnormalities of regulation of PRL secretion and impaired glucose tolerance, independent of antipsychotic treatment." (PMID 30068291, 2018). "In our study, the conventional metformin dose (1–2 g/day) used to treat diabetes mellitus in schizophrenia with co-morbid T2DM also had the same function of lowering PRL levels and showed a negative dose-dependence of metformin dose and PRL levels." (PMID 36816406, 2023).
schizophrenia (continued). "Interestingly, previous studies showed that first-episode schizophrenia populations without or minimal antipsychotic exposure present with higher prevalence of MAs, including lipid profile disturbances, reduced uric acid levels, elevated homocysteine and prolactin levels." (PMID 34305687, 2021). "While the use of prolactin-raising AP could not be dismissed as a possible contributing factor, there was some evidence to suggest that reduced BMD in female patients represents diminished estrogen-induced neuroprotection, in support of the estrogen hypothesis of schizophrenia." (PMID 26309037, 2015).